IL2 (interleukin 2)
Diseases named in the same sentence as IL2 in open-access papers (continued):
Sharing a sentence is not in itself a finding about the gene and the disease.
rubella (3 papers, 2010 to 2014). A viral infection caused by the rubella virus. "During rubella vaccinations, the A allele was associated with lower rubella virus specific IL-2 secretion and the G allele with higher IL-2 secretion." (PMID 25205466, 2014). "Since cytokines are important for the development and shaping of innate and adaptive immune responses to rubella, we examined associations between extended haplotypes and rubella virus-specific cytokine (IFN-γ, IL-2, IL-6, TNF-α, and GM-CSF) secretion levels." (PMID 20668555, 2010).
scleritis (3 papers, 2019 to 2023). Inflammation of the sclera. "Moreover, histocompatibility complex (MHC), TNF, IL1A, IL1β, IL2, IFNγ, and TNF were widely present in the top five disease signaling pathways, suggesting that these genes may be involved in the development of scleritis." (PMID 37063831, 2023).
septic arthritis (3 papers, 2016 to 2024). "The administration of a low-dose IL-2 treatment through intraperitoneal injection of a recombinant adeno-associated virus vector effectively mitigated the severity of septic arthritis." (PMID 38410388, 2024). "This intervention also maintained the host’s capacity to clear the infection, indicating a protective role of IL-2 in septic arthritis." (PMID 38410388, 2024). "Pre-treatment with IL2 gene therapy dampens detrimental immune responses but preserves appropriate host defense, which alleviates S. aureus septic arthritis in a mouse model." (PMID 32111171, 2020).
synovial sarcoma (3 papers, 2018 to 2023). "We hypothesized that Ss infection would be associated with alterations in memory T cell subset distribution, alterations that could be reflective of changes in IL-2, IL-4, IL-7, IL-9 and IL-15." (PMID 29795573, 2018). "successfully investigated the antitumor response of NY-ESO-1-specific TCRs with high dose interleukin-2 in refractory synovial sarcoma (SS)." (PMID 37007160, 2023). "In our previous study, we have shown that IL-2 levels have been significantly diminished in Ss infection when compared to uninfected individuals." (PMID 29795573, 2018).
synovitis (3 papers, 2005 to 2024). Inflammation of a synovial membrane. "Early RA synovial fluid was characterized by significantly elevated levels of T cell related cytokines (IL-2, IL-4, IL-13 and IL-17) and stromal cell and macrophage related cytokines (EGF, bFGF, IL-1 and IL-15) when compared with synovial fluid from patients with other early synovitis." (PMID 15987480, 2005).
teratoma (3 papers, 2008 to 2024). A non-seminomatous germ cell tumor characterized by the presence of various tissues which correspond to the different germinal layers (endoderm, mesoderm, and ectoderm). "However, in syngeneic 129Sv mice the ES cells gave rise to teratomas despite these mice have functional NK cells which can kill the ES cells in vitro after IL-2 stimulation." (PMID 18612432, 2008). "Copy number deletion of SETDB2 and IL2 only appeared in immature teratoma (43% and 36%, respectively), but not in mature teratoma (p = 0.051 and 0.115, respectively)." (PMID 36457486, 2022).
thymus atrophy (3 papers, 2022 to 2024). Acquired diminution of the size of the thymus associated with wasting as from death and reabsorbtion of cells, diminished cellular proliferation, decreased cellular volume, pressure, ischemia, malnutrition, reduced function or malfunction, or hormonal changes. "Thymus atrophy is linked not only to reduced thymulin activity but also to lower levels of IL-2 and alterations in IL-2-induced signaling pathways, all of which contribute to increased lymphocyte apoptosis and reduced proliferation." (PMID 39599720, 2024).
tic disorder (3 papers, 2020 to 2023). Disorders characterized by recurrent TICS that may interfere with speech and other activities. "The relationship between IL-2 and the severity of tic disorder may indicate that cellular immunity is involved in tic disorder." (PMID 35087475, 2021). "It is noteworthy that the dopaminergic system may be involved in the mechanism of tic disorders, and a study have shown that IL-2 can enhance the release of dopamine." (PMID 35087475, 2021).
triple-negative breast carcinoma (3 papers, 2021 to 2023). An invasive breast carcinoma which is negative for expression of estrogen receptor (ER), progesterone receptor (PR), and human epidermal growth factor receptor 2 (HER2). "A statistically significant increase in the content of MCP-1, IL-1β, IL-2, IL-4, and IL-10 was found in triple-negative breast cancer." (PMID 36286034, 2022).
tuberculous pleurisy (3 papers, 2011 to 2016). "IL-1β, IL-2, IL-6, TNF-α, PAI-1, and t-PA levels in pleural fluids of 40 patients with tuberculous pleurisy and 38 patients with tuberculous empyema were measured." (PMID 27034588, 2016). "In addition, CD4+ T cells expressing different combinations of IFN-γ, IL-2, TNF-α, IL-17A, and IL-22 have been described in tuberculous pleurisy." (PMID 23451159, 2013). "However, following stimulation with MTB-specific peptides of ESAT-6/CFP-10, CD4+CD69+ T cells from the same patients with tuberculous pleurisy expressed high levels of IFN-γ, IL-2 and TNF-α, indicating that the response was MTB-specific." (PMID 21887301, 2011).
urinary tract infection (3 papers, 2010 to 2022). "Previous study showed that cytokine antagonist IL-1RA is elevated in plasma of aged patients and IL-2 production in vitro was lower with urinary tract infections compared to healthy aged." (PMID 20716329, 2010). "Although elevated levels of urinary cytokine IL-2 were associated with a favorable response to intravesical BCG, elevated levels of the non-specific cytokines IL-6 and IL-8 were observed due to concurrent urinary tract infections." (PMID 31216733, 2019).
xerostomia (3 papers, 2017 to 2024). Dryness of the mouth resulting from reduced salivary secretion. "Based on the one-way analysis of variance (ANOVA), the individuals who experienced dry mouth had significantly lower levels of saliva IL-2 and TNF-α, and higher levels of serum IL-12p70 and IL-10." (PMID 36846089, 2023). "Among the inflammatory cytokines assessed - IL-6, TNF-α, IFN-γ, IL-10, IL-12p70, IL-1β, IL-8, IL-13, IL-2, IL-5, IL-7 and IL-17A, xerostomia correlated with lower levels of saliva IL-2 and TNF-α, and elevated levels of serum IL-12p70 and IL-10 (p < 0.05)." (PMID 36846089, 2023). "We found that saliva IL-2 and TNF-α levels were lower, and serum IL-12p70 and IL-10 (p < 0.05) higher in patients with xerostomia than those without." (PMID 36846089, 2023).
acne (2 papers, 2022 to 2024). An inflammatory process of the sebaceous glands which is characterized by comedones, nodules, papules and/or pustules on the skin. "The significant overexpression of pro-inflammatory markers such as Toll-like receptor-4 and interleukin-2 was observed both in the normal-appearing skin and inflammatory skin of acne patients with atrophic scars compared to acne patients without atrophic scars." (PMID 35806952, 2022). "Significantly increased expression of TLR-4, IL-2, IL-10, and TIMP-2 and decreased MMP-9 havebeen demonstrated in patients with acne prone to scarring." (PMID 38398480, 2024).
acral melanoma (2 papers, 2020 to 2022). "The first responding patient, a 31-year-old man with acral melanoma, had previously received adoptive T-cell therapy with high-dose IL-2, ipilimumab, and pembrolizumab." (PMID 32238921, 2020). "Also, patients with acral melanoma showed lower levels of IL-2 than non-acral melanoma." (PMID 36405903, 2022).
Adrenal insufficiency (2 papers, 2013 to 2023). Insufficient production of steroid hormones (primarily cortisol) by the adrenal glands. "A third patient, also treated at the high dose of IL-2, discontinued due to a combination of adrenal insufficiency and dyspnea not otherwise specified, and was treated with reater than 40 mg prednisone daily and inhaled steroids." (PMID 36845705, 2023).
age (2 papers, 2021 to 2025). A temporal measurement of the time period elapsed since an identifiable point in the life cycle of an organism. "Again, this phosphorylation defect is not evident in CD8+ T cells from the patient, which only showed reduced fold induction of STAT5 phosphorylation when compared to age-related HD at higher IL-2 concentration levels." (PMID 40170851, 2025).
alexithymia (2 papers, 2021 to 2026). An agnosia that is a deficiency in understanding, processing, or describing emotions. "Lymphocyte subset counts (CD4, CD8), in vitro production of interleukin 1β (IL-1β), IL-2, IL-4, and IL-10 by phytohemagglutinin stimulated peripheral blood lymphocytes, as well as serum cortisol levels, were compared between women with and without alexithymia." (PMID 34987425, 2021).
allergic respiratory disease (2 papers, 2021). A respiratory system disease with a basis in a pathological type I hypersensitivity reaction. "The rationale of this strategy derives from the data that JAK is a tyrosine kinase involved in the signaling of T cell receptor and of several cytokines that play a role in allergic respiratory disease, such as IL-2, IL-4 and IL-9." (PMID 34680614, 2021). "The rationale of this strategy stems from the notion that JAK is a tyrosine kinase involved in the signaling of T cell receptor and of several cytokines that play a pivotal role in allergic respiratory disease, such as IL-2, IL-4 and IL-9." (PMID 34680614, 2021).
aortic aneurysm (2 papers, 2018 to 2022). A ruptured aneurysm located in the wall of the proximal portion of the descending aorta proceeding from the arch of the aorta. "In contrast, expansion of Tregs via IL‐2 complex treatment resulted in a smaller aortic aneurysm diameter and fewer TUNEL‐positive SMCs." (PMID 35332699, 2022).
Aortic dissection (2 papers, 2014 to 2025). Aortic dissection refers to a tear in the intimal layer of the aorta causing a separation between the intima and the medial layers of the aorta. "The previous microarray study also observed that IL-2, -6 and -8 genes were up-regulated in aortic dissection." (PMID 24586754, 2014).
Arthralgia (2 papers, 2015 to 2022). "More importantly, we identified an immune mediator signature dominated by proinflammatory cytokines, which include interferon α and γ and interleukin 2, 2R, 6, 7, 12, 15, 17, and 18, across different patient cohorts of CHIKV load associated with arthralgia." (PMID 25635123, 2015). "ROC curve analysis yielded an optimal cut-off IL-2, IL-10, and INF-γ levels of 2.67, 5.93, and 5.32 pg/ml for the presence of arthralgia." (PMID 36408259, 2022). "The serological IL-2, IL-6 and INF γ levels in the presence of arthralgia elevated, while Th17 and Th17/Treg decreased." (PMID 36408259, 2022).
aspergillosis (2 papers, 2020 to 2022). Aspergillosis is an infection, growth, or allergic response caused by the Aspergillus fungus. "It is noteworthy that in the acute phases of pulmonary aspergillosis, IL-2 released by DC1 mitigated and controlled the pathogenicity of Th17 cells, representing a regulatory process specifically instructed by CD103+DC1 in response to the fungus." (PMID 36012781, 2022).
atopic asthma (2 papers, 2010 to 2023). An asthma that is characterized by symptoms that are triggered by an allergic reaction caused by inhaled allergens such as dust mite allergen, pet dander, pollen and mold. "In this study intracellular cytokine expression of IL-2, IL-4, IL-10, IL-13, IFN-γ, and TNF-α in CD4+ and CD8+ T cells in children with atopic asthma were measured by flow cytometry." (PMID 21197090, 2010).
attention deficit-hyperactivity disorder (2 papers, 2012 to 2020). A disorder characterized by a marked pattern of inattention and/or hyperactivity-impulsivity that is inconsistent with developmental level and clearly interferes with functioning in at least two settings (e.g. at home and at school). "Novel research has also demonstrated the involvement of IL-1β, IL-2, IL-8, and TNFα dysfunction in neurological diseases including attention-deficit hyperactivity disorder (ADHD) and delayed cognitive development." (PMID 22768323, 2012). "Nevertheless, both autism spectrum disorders (ASD) and attention deficit hyperactivity disorder (ADHD) are associated with increases in adaptive immune (T) cell cytokines, specifically Th2-like cytokines (IL-4, IL-6, and/or IL-10), or decreases in Th2-like cytokines (IL-2 and/or IFNγ)." (PMID 33424735, 2020).
autoimmune type 1 diabetes (2 papers, 2021 to 2022). Autoimmune disease wherein the body's own immune system attacks and destroys the cells within the pancreas that produce insulin. "It has been reported that SEA can protect against type 1 autoimmune diabetes via increasing Foxp3 expression in a TGF-β-dependent manner, along with upregulating C-type lectins, IL-10, and IL-2 on dendritic cells (DC)." (PMID 36304936, 2022).
B-cell acute lymphoblastic leukemia (2 papers, 2021 to 2025). A neoplasm of lymphoblasts committed to the B-cell lineage, typically composed of small to medium-sized blast cells. "Our results show that curcumin enhances the cytotoxic activity of CAR T-cells against Nalm-6, a B-cell acute lymphoblastic leukemia model, while reducing the production of pro-inflammatory cytokines, including IL-2 and IFN-γ." (PMID 40298832, 2025).
B-cell lymphoblastic leukemia (2 papers, 2021 to 2024). "In studies, patients with B-cell lymphoblastic leukemia following CAR-T cell therapy presented elevated levels of IL-1α, IL-2, IL-3, IL-5, IL-6, IL-8 IL-10, IL-15, IFN- γ, procalcitonin, CRP, G-CSF, GM-CSF, and MCP-1, and their levels were linked to the severity of neurotoxicity." (PMID 39409959, 2024).
Bell's palsy (2 papers, 2020 to 2025). Partial or complete paralysis of the facial muscles of one side of a person's face. "Experimentally, increased IL-2 and IL-4 were detected in HSV-1-induced facial nerve palsy as an indication of an immune response." (PMID 41366113, 2025). "Previous studies have revealed that the expression of collagen, IL-1, IL-2, IL-4, TGF-β, and other inflammatory factors is decreased after using high-doses of methylprednisone for femoral head necrosis, shoulder joint injury, spinal cord injury, Bell's palsy, and other diseases." (PMID 32377419, 2020).
bladder urothelial carcinoma (2 papers, 1999 to 2022). "Transitional cell carcinoma of the bladder is one of the human cancers most responsive to immunotherapy, and local interleukin-2 (IL-2) production appears to be an important requirement for immunotherapy to be effective." (PMID 10070868, 1999). "For example, FOXQ1 expression inhibited activation of the IL6/JAK/STAT3 signaling pathway, IL2/STAT5 signaling pathway, allograft rejection pathway, apical junction pathway, and complement pathway in bladder urothelial carcinoma." (PMID 36118871, 2022).
burn (2 papers, 2012). A traumatic injury involving interruption of tissue cohesiveness that results from exposure to caustic chemicals, extreme heat, extreme cold or excessive radiation. "Burn injury results in reductions in interleukin-2 (Il-2) production, T-cell and NK cell cytotoxicity, and helper- to- suppressor T-cell ratio (HSR)." (PMID 22899912, 2012). "Increased levels of IL-1α, IL-2, IL-4, IL-10, IFN-γ and TNFα could be detected in culture media of burn injury skin cultures." (PMID 22359539, 2012).
cataract (2 papers, 2014 to 2023). Partial or complete opacity of the crystalline lens of one or both eyes that decreases visual acuity and eventually results in blindness. "In the PHA-stimulated PBMC cultures, IL-2, IFN-γ, IL-6, and IL-17A were significantly increased, and the IL-6 level was significantly higher in the VKH patients than in the BD and AR cataract patients." (PMID 25303043, 2014). "We inferred that the expressions of IL-2, IL-4, IL-6, IL-10, IL-17A, and IFN-γ were the most likely to differ between inflammatory cataracts that are secondary to BD and VKH and AR cataracts." (PMID 25303043, 2014). "The expression levels of IL-2, IL-4, IL-6, IL-10, IL-17A, and IFN-γ were analyzed in the AqH, and PHA-stimulation and non-PHA-stimulated cultures of PBMCs from these three types of cataract patients." (PMID 25303043, 2014). "The expressions of interleukin-2 (IL-2), IL-4, IL-6, IL-10, IL-17A, and interferon-γ (IFN-γ) were analyzed in aqueous humor (AqH), phytohemagglutinin (PHA)-stimulated and non-PHA-stimulated cultures of peripheral blood mononuclear cells (PBMCs) from the three types of cataract patients." (PMID 25303043, 2014).
Chagas cardiomyopathy (2 papers, 2023 to 2025). A disease of the cardiac muscle developed subsequent to the initial protozoan infection by trypanosoma cruzi. "Research suggests that individuals at high risk of sudden death in Chagas cardiomyopathy exhibit elevated serum levels of IFN-γ, TNF-α, IL-6, IL-2, IL-10, and IL-4 compared to those at low risk." (PMID 39907396, 2025).
childhood asthma (2 papers, 2021 to 2022). "Furthermore, IL-2 can modulate the differentiation of CD4+ T helper (Th) cell subsets, including T-helper 1 (Th1), T-helper 2 (Th2), T-helper 17 (Th17), and regulatory T (Treg) cells, the key pathways in allergic and non-allergic inflammation and childhood asthma." (PMID 33810791, 2021).
Chlamydia infection (2 papers, 2019 to 2021). "Since cellular immunity is a key component of the protective immune response following Chlamydia infection, we evaluated the magnitude of Th1 (IFN-γ, IL-2, IL-12, IL-18), Th2 (IL-4) and anti-inflammatory (IL-10) cytokines (Expt." (PMID 34001988, 2021).
Chorea (2 papers, 2024 to 2025). Chorea (Greek for 'dance') refers to widespread arrhythmic involuntary movements of a forcible, jerky and restless fashion. "A study found that HD patients with severe motor and non-motor symptoms (excluding chorea) had higher IL-2 levels compared to those with milder symptoms, suggesting that IL-2 elevation is linked to disease severity, which could explain the lack of CGA’s effect on IL-2 in our early-stage HD model." (PMID 40038202, 2025).
chronic gastritis (2 papers, 2016 to 2020). Inflammation of the stomach that is chronic in nature. "H. pylori infection results in increased expression of TNFA, IL6, IL12A and IL2 in the gastric mucosa, in addition to the effect of chronic gastritis, and for TNF‐α and IL‐2 proteins, this increase was mainly observed in inflammatory cells." (PMID 26945693, 2016). "Immunohistochemical analysis allowed us to show expression and cell localization of TNF‐α, IL‐1β, IL‐2, IL‐12‐p40 and TGF‐β‐RII proteins in the normal mucosa, and in H. pylori infected and non‐infected chronic gastritis." (PMID 26945693, 2016). "Herein, we assessed whether H. pylori infection and its eradication, beyond its cagA virulence genotype, change the expression of inflammatory mediators (TNFA, IL6, IL1B, IL12A, IL2 and TGFBRII) in chronic gastritis patients." (PMID 26945693, 2016). "mRNA and protein expression of TNFA, IL6, IL1B, IL12A, IL2 and TGFBRII and miRNAs miR‐103a‐3p, miR‐181c‐5p, miR‐370‐3p, miR‐375 and miR‐223‐3p were evaluated in tissue samples from 20 patients with chronic gastritis H. pylori negative (Hp−) and 31 H." (PMID 26945693, 2016).
Chronic Heart Failure (2 papers, 2018 to 2023). "Research has shown that patients with chronic heart failure often have increased levels of IL-2 and IL-1." (PMID 37761997, 2023).
clear cell carcinoma (2 papers, 2018 to 2021). "For an adequate follow-up and informed decisions about adjuvant immunotherapy with interleukin-2 and interferon alpha after cholecystectomy, gallbladder metastasis of RCC should be differentiated from primary clear cell carcinoma of the gallbladder through histochemical examination." (PMID 29855393, 2018).
coccidioidomycosis (2 papers, 2005 to 2023). A fungal infection caused by Coccidioides immitis. "In patients with pulmonary coccidioidomycosis, several cytokines were increased in high concentrations, including granulocyte-macrophage colony-stimulating factor (GM-CSF), interleukin-1β (IL-1β), interferon gamma (IFN-γ), IL-2, IL-13, and tumor necrosis factor alpha (TNF-α)." (PMID 37233224, 2023).